BRCA1 (BRCA1 DNA repair associated)
Diseases named in the same sentence as BRCA1 in open-access papers (continued):
Sharing a sentence is not in itself a finding about the gene and the disease.
ovarian carcinoma (continued). "A total of 190 BRCA1 mutations and 169 BRCA2 mutations were detected in the enrolled ovarian cancer population." (PMID 38817903, 2024). "Overexpressed miR-182 and miR-9 mediate the downregulation of BRCA1 and increase sensitivity to cisplatin and PARPis in ovarian cancer." (PMID 38539161, 2024). "BRCA1 and BRCA2 are tumor suppressor genes located on chromosome 17q21 and 13q12, respectively, and are responsible for an increased risk of breast and ovarian cancer development." (PMID 38792636, 2024). "While BRCA1 and RAD51 germline mutations are well-characterised in breast and ovarian cancer, their role in renal cell carcinoma is still largely unexplored." (PMID 38512353, 2024). "To further confirm that HMGA1 promotes DNA repair via the NHEJ pathway, we knocked down BRCA1 and BRCA2 in TYK‐nu ovarian cancer cells to simulate a homologous recombination deficiency (HRD) state." (PMID 39690136, 2024). "Epithelial ovarian cancer (EOC) has been reported to account for 95% of all ovarian cancers, with 11%–90% of the EOC associated with alterations in the expression of BRCA1 protein due to mutations in the BRCA1 gene." (PMID 39502381, 2024). "Immunohistochemical staining on 214 ovarian tumor patients was performed to investigate the findings, thus demonstrating a gradual decrease or even disappearance of BRCA-1 gene expression in benign-borderline-malignant ovarian tumors." (PMID 39281319, 2024). "For example, many ovarian cancer patients eventually develop poly(ADP)-ribose polymerase (PARP) inhibitors and platinum resistance via reversion mutations in BRCA1/2." (PMID 37310942, 2023). "While mutations that disrupt E3 ligase activity and stability of the BRCA1- BARD1 complex lead to a predisposition for breast and ovarian cancer, the specific requirement for E3 ligase activity in tumor suppression is not known." (PMID 36716349, 2023). "Women with a BRCA1/2 germline pathogenic variant (GPV) are advised to undergo surgery to remove their ovaries and fallopian tubes at a young age to prevent tubal/ovarian cancer." (PMID 37046756, 2023). "The Japanese Gynecologic Oncology Group is currently conducting a basket trial on niraparib monotherapy for any gynecological cancer (except ovarian cancer) with BRCA1/2 genomic alterations, which targets a rare fraction of each cancer type." (PMID 38201563, 2023). "In-frame insertions of intronic sequences were observed in BRCA1/2 genes from three patients with breast or ovarian cancer (Cases 7, 8, and 9)." (PMID 37900184, 2023). "Several studies observed that most sporadic breast and ovarian cancers showed low levels of BRCA1 messenger RNA (mRNA) and protein expression." (PMID 36631481, 2023). "In a study of 292 women with ovarian cancer, it was observed that 120 of the cases had ≤10% of the IHC nuclear staining of BRCA1 and 59% of women expressed >10% of BRCA1 staining which was classified as overexpression of BRCA1." (PMID 36768291, 2023). "To validate the BRCA1-specific function of histone H1 in fork protection, we then repeated DNA fibre experiments in BRCA1-mutant UWB1.289 ovarian cancer cells." (PMID 37364916, 2023). "We used an isogenic pair of BRCA1-deficient (HR-deficient) UWB1.289 vs. BRCA1-proficient (HR-proficient) UWB1.289+BRCA1 ovarian cancer cells (herein referred to as “UWB” and “UWB+BRCA1”) for constructing an in vitro model of PARPi resistance." (PMID 37568590, 2023). "BRCA1 and BRCA2 germline mutations are the most potent recognized genetic risk factors for epithelial ovarian cancer and are detected in 6–15% of women diagnosed with this disease." (PMID 37621847, 2023). "Still, upstream regulators of NNMT in cancer were shown to be diverse, as in BRCA1 for ovarian cancer, HNF1β for thyroid cancer, and SHH for pancreatic cancer." (PMID 36750850, 2023). "In our cohort, ovarian cancer was the second most common type of neoplasia detected during follow-up for both BRCA1 and BRCA2 patients." (PMID 38067403, 2023).
ovarian carcinoma (continued). "Analyzing the 20 BRCA1-methylation-positive ovarian cancer patients separately revealed similar results to the whole group of OC patients, where the expression of miR-155-5p was significantly higher in patients as compared to controls (p = 0.043)." (PMID 37240365, 2023). "It has been previously reported in an ovarian cancer patient of European ancestry in The Cancer Genome Atlas and showed a neutral impact on the BRCA1 function in a cell-based homology-directed recombination assay." (PMID 37951914, 2023). "It includes the surgical removal of the fallopian tubes and ovaries bilaterally and has proved its effectiveness in preventing ovarian cancer in BRCA1/2 carriers." (PMID 36826146, 2023). "It has been well-established that mutations in BRCA1 and BRCA2, compromising functions in DNA double-strand break repair (DSBR), confer hereditary breast and ovarian cancer risk." (PMID 37198153, 2023). "The implementation of mainstream BRCA1/2 testing for patients diagnosed with epithelial ovarian cancer occurred due to the development of PARPi as standard therapy." (PMID 38201604, 2023). "For ovarian cancer, germline testing for BRCA1/2 is informative for selecting patients for PARP inhibitor therapy." (PMID 37664050, 2023). "In the MEDIOLA basket studies, all cohorts were histotype-limited, with the advanced breast and relapsed ovarian cancer cohorts permitting only germline BRCA1/2 alterations and platinum-sensitive disease." (PMID 37365284, 2023). "The tumor suppressor gene BRCA1 is involved in breast and ovarian cancer development, mainly through decreased levels of BRCA1 mRNA." (PMID 36769304, 2023). "For example, germline mutations in BRCA1 and BRCA2 tumor suppressor genes increase the risk of breast and ovarian cancer in humans, and Brca1 and Brca2 genes participate in the embryonic development and differentiation of mammary glands in mice." (PMID 37239953, 2023). "In breast and ovarian cancers, germline/somatic mutations in key components of the HR-mediated DSB repair pathway, like BRCA1/2, have been known to cause HR deficiency (HRD) in tumors." (PMID 37540752, 2023). "Intriguingly, BRCA1 deficiency has also been linked to POA and SETX deletion has been observed in ovarian cancers with a similar extent than BRCA1 deletions." (PMID 37147318, 2023). "Population-based studies have shown that BRCA1 and BRCA2 mutations are found in roughly 15% of all ovarian cancer cases." (PMID 37228496, 2023). "BRCA1 c.5309G>T mutation is located in the functionally important BRCA1 carboxyl terminal (BRCT) domain, a domain known to harbor missense substitutions associated with increased risk of breast/ovarian cancer." (PMID 37055759, 2023). "BRCA1 and BRCA2 genes are recognized as the primary inherited causes of breast and ovarian cancer since they were discovered in 1990s." (PMID 38274092, 2023). "Since the efficacy of these screening approaches is still unclear, prophylactic ovarian surgery is an essential option for patients with confirmed BRCA1 or BRCA2 mutations or a strong family history of breast and/or ovarian cancer." (PMID 37370973, 2023). "First, mice were inoculated with A2780 ovarian cancer cells (BRCA1/2 WT) followed by oral treatment with olaparib, PRT543, or in combination." (PMID 37861290, 2023).
ovarian carcinoma (continued). "These screens have mainly been carried out in a BRCA1- or BRCA2-deficient context, using in cellulo or in vivo mouse models for breast or ovarian cancer." (PMID 37609662, 2023). "Women who inherited the pathogenic variants (PV) of the BRCA1 or BRCA2 (BRCA1/2) genes have increased risks of developing breast and ovarian cancers (OCs)." (PMID 36658289, 2023). "For instance, miR-9-5p functions as an oncomiR, acting against curcumin and paclitaxels’ cytotoxic synergistic effects by inhibiting BRCA1 in ovarian cancer cases." (PMID 37925170, 2023). "More H3K27ac clustered around the genomic locus of the HRD-EXCUTE hub genes in BRCA1-null ovarian cancer cells." (PMID 37063431, 2023). "A comprehensive understanding of BRCA1’s functions remains pivotal for formulating effective approaches in diagnosing, preventing, and treating breast and ovarian cancers." (PMID 37762577, 2023). "Using this approach, we report that the BDP1 alterations identified in ovarian cancer were deep deletions with decreased expression correlating with increased serous ovarian cancer stage similar to known critical cancer drivers, BRCA1 and BRCA2." (PMID 36305848, 2023). "Improved prognosis with higher partial response (PR) and complete response (CR) rates to platinum-based chemotherapy and longer PFI, has been observed in patients who are BRCA1/2-mutant carriers with ovarian cancer." (PMID 36922847, 2023). "Because the GIS distributions in BRCA1/2-deficient ovarian and TNBC samples were similar, the thresholds used for ovarian cancer were applied to the TNBC samples in this study." (PMID 37589839, 2023). "Among these analyses, those related to the BRCA1 and BRCA2 genes emerge as extremely important since their mutations are responsible for approximately 5 to 10% of breast and 15% of ovarian cancers (Melchor and Benítez 2013)." (PMID 37723374, 2023). "We analysed germline and tumour BRCA1/2 test results from patients treated for epithelial ovarian cancer at our specialist oncological referral centre." (PMID 38201604, 2023). "LNCaP and C4-2B cells are relatively more sensitive to olaparib in contrast to 22Rv1 and DU145 cells, but less sensitive when compared to BRCA1-null ovarian cancer UWB1.289 cells." (PMID 36650183, 2023). "This demonstrates that low BRCA1 expression can be used as a positive prognostic factor in ovarian cancer and to predict an enhanced response to platinum chemotherapy." (PMID 36768291, 2023). "Currently, we know that defective homologous recombination DNA repair imposed by BRCA1 or BRCA2 deficiency sensitizes cells to and is currently used in the treatment of ovarian cancer." (PMID 37686547, 2023). "Realistically, only 15–25% of ovarian cancers harbor BRCA1/2 alterations, and they are even rarer in other tumor types." (PMID 37761329, 2023). "Risk-reducing bilateral salpingo-oophorectomy (RRSO) is an effective prophylactic surgery provided to premenopausal women carrying BRCA1 or BRCA2 mutations and presenting an increased risk of developing breast or ovarian cancer." (PMID 36826146, 2023). "Homozygous BRCA1 promoter methylation predicts response to rucaparib in a cohort of 21 ovarian cancer patients in the ARIEL2 trial." (PMID 36611214, 2023). "Two families were identified to carry the BRCA1 c.-107A > T SNV and in these two families this variant was associated with an increased risk of breast and ovarian cancer." (PMID 36112334, 2023).
ovarian carcinoma (continued). "This tool can be a valuable resource for researchers and clinicians as it can assist in the identification of potential disease-causing variants in BRCA1 and BRCA2 genes, which are associated with an increased risk of breast and ovarian cancer." (PMID 38149678, 2023). "Beyond established genetic mutations like BRCA1 and BRCA2, researchers are exploring the contribution of other genetic alterations and environmental factors to ovarian cancer risk." (PMID 38084173, 2023). "Over the last two decades, there has been an increase in genetic testing for cancer, for example, between 2007 and 2019 one study showed a threefold increase in germline BRCA1/2 testing in ovarian cancer." (PMID 37258796, 2023). "BRCA1 c.5266dup has previously been found in prostate cancer and pancreatic cancer, in addition to its known role in ovarian cancer." (PMID 37791908, 2023). "Compared to control, CD47 blockade therapy with SIRPa-Fc decoy receptor (TTI-621) enhanced macrophage-mediated in-vitro phagocytosis of ovarian cancer cells (BRCA1 mutated, UWB1.289 and its counter cell line with BRCA1 wild type, UWB1.289)." (PMID 37468567, 2023). "A series of genetic changes, including germinal mutations in BRCA1/2, intratumoral BRCA1/2 mutations, BRCA1 promoter methylation, and other possible genetic causes, may indicate the loss of homologous recombination function in at least 50% of patients with ovarian cancer, according to TCGA data." (PMID 37761329, 2023). "Most intriguingly, the BRCA1/2 mutant ovarian cancers respond much more frequently than other types of cancers." (PMID 37035242, 2023). "The KOHBRA study, published in 2011, estimated BRCA1/2 LGRs to be high (~20–23%) in the Korean hereditary breast or ovarian cancer populations." (PMID 37013911, 2023). "The results of our study show that BRCA1/2 genetic testing is well accepted in a group of long-surviving patients with a previous diagnosis of breast and ovarian cancer, even more than 10 years after the first cancer diagnosis with 78% adherence." (PMID 37723374, 2023). "BRCA1 and BRCA2 play a central role in DNA repair and their germline pathogenic variants (gBRCA) confer a high risk for developing breast and ovarian cancer." (PMID 37119509, 2023). "Studies have found that ovarian cancer tissues have higher transcriptome-level BRCA1/2 expression which is in line with our finding." (PMID 36899893, 2023). "Women with BRCA1 or BRCA2 gene mutations are at increased risk of breast and ovarian cancer and often undergo operations to remove both their ovaries in order to prevent ovarian cancer." (PMID 36900415, 2023). "For example, in the French-Canadian founder population, twenty variants in BRCA1, BRCA2, and PALB2 that predispose families to breast and ovarian cancer have been identified at increased frequencies." (PMID 36927983, 2023). "Taking into consideration previous studies that have investigated the landscape of germline LGRs in breast and ovarian cancer, we conclude that our cohort contains a similar proportion of BRCA1/2 LGRs as was previously reported." (PMID 37013911, 2023). "Pathogenic variants (PVs) in BRCA1 and BRCA2 increase the lifetime risks of breast and ovarian cancer." (PMID 37887578, 2023). "The identification of BRCA1 and BRCA2 pathogenic variants is recommended as an effort of primary prevention for epithelial ovarian cancer." (PMID 37143950, 2023). "Re-expression of BRCA1 protein by de-methylation was demonstrated to occur at the time of recurrence in a patient with PARPi-resistant epithelial ovarian cancer." (PMID 37190285, 2023).
ovarian carcinoma (continued). "Since the identification of the hereditary breast and ovarian cancer genes BRCA1 and BRCA2 (BRCA1/2) in 1994–5, the concept of hereditary cancer syndromes has been widely accepted by the medical community." (PMID 37084156, 2023). "The recent success of Poly (ADP-ribose) polymerase (PARP) inhibitors has led to the approval of four different PARP inhibitors for the treatment of BRCA1/2-mutant breast and ovarian cancers." (PMID 37509303, 2023). "We found that BRCA1 promoter methylation was present in 10.3% of unselected ovarian cancer cases and in 6.5% of healthy controls, what corresponded to slightly (about 50%) increased risk of ovarian cancer (OR 1.65, 1.12-2.40, p = 0.01)." (PMID 37434214, 2023). "In the context of BRCA1-mutated breast and ovarian cancers, ELC exhibited selective sensitivity to cancer cells with mutant BRCA1 and showed synergistic effects when combined with DNA-damaging agents or PARP inhibitors." (PMID 37864163, 2023). "To conclude, although mosaicism for BRCA1 and BRCA2 variants seems to be rare, low-level mosaic mutations can contribute to the aetiology of breast and ovarian cancer susceptibility." (PMID 36833429, 2023). "Through modified segregation analysis including families from this study, risk estimates for breast and ovarian cancer have been refined for PTVs in RAD51C, RAD51D, PALB2 and for the moderate penetrance missense variant BRCA1 c." (PMID 37563628, 2023). "A loss of function mutations in the BRCA1 and BRCA2 genes is associated with a higher likelihood of the development of breast and ovarian cancers." (PMID 37366887, 2023). "Compared to ovarian cancer, the GIS distribution of BRCA1/2-deficient samples was shifted lower for ER + BC (p = 0.015), but not TNBC (p = 0.35)." (PMID 37589839, 2023). "According to the NCCN guideline, BRCA1, BRCA2, BRIP1, RAD51C and RAD51D have been proved with susceptibilities of ovarian cancer, and their deleterious mutation carriers were recommended for risk reducing salpingo-oophorectomy (RRSO)." (PMID 37386498, 2023). "The genetic predispositions of defective BRCA1 and/or BRCA2 (the second most common mutations in ovarian cancer) genes are responsible for only 10–20% of all ovarian cancer cases, with the genetic marker increasing a patient’s risk by 15–60%." (PMID 36671544, 2023). "Methylation status of BRCA1/2 gene in ovarian cancer patients was assessed using methylation-sensitive high-resolution melting (MS-HRM), and classified as positive or negative." (PMID 37434214, 2023). "Women with a family history of breast or ovarian cancer are encouraged to undergo genetic screening for a panel of genes including BRCA1 (MIM: 113705)." (PMID 37578980, 2023). "It is well-known that BRCA1 and BRCA2 carriers are at increased risk for breast and ovarian cancers, and BRCA2 carriers are at increased risk for pancreatic and prostate cancers." (PMID 36861435, 2023). "The wider implication of possible under reporting of BRCA1 Exon 13 duplication can be seen in two recent publications in which only one case of this large rearrangement was reported in over 22,000 ovarian cancer tissue samples tested using the myChoice® CDx." (PMID 38201604, 2023). "It has been found that inhibiting VEGFR3 and blocking the expression of VEGF-C in ovarian cancer can reduce BRCA1 and BRCA2, which is conducive to chemotherapy and the subsequent use of PARP inhibitors." (PMID 36611214, 2023). "Within the BRCA1/2 mutant ovarian cancer cohort, interim results suggest an ORR of 71.9% (95% CI = 53–86)." (PMID 37190285, 2023).